INS (insulin)
Diseases named in the same sentence as INS in open-access papers (continued):
Sharing a sentence is not in itself a finding about the gene and the disease.
diabetes (continued). "Further experiments using programmed insulin and leptin administration and monitoring, combined with planned diet regimes, can improve our understanding about progression of metabolic diseases like obesity and diabetes." (PMID 26540285, 2015). "Serum levels of mouse insulin became negligible after induction of diabetes." (PMID 26064925, 2015). "Within this new system the diabetes convention could focus on diabetics with complex insulin schemes or severe complications." (PMID 26171143, 2015). "Besides, zinc is important for insulin synthesis and action in both, normal and diabetes mellitus condition." (PMID 25653669, 2015). "In addition, the impact of HFD on β-cell functions such as glucose-induced insulin secretion (GSIS) at onset of the diabetes and following insulin therapy in both HFD and LFD-treated animals will be evaluated." (PMID 25633992, 2015). "Of all the diabetes medications, insulin is the most effective in lowering the glycemia." (PMID 26157708, 2015). "HDL-C might have the ability to stimulate the release of insulin, which reduces the possibility of developing diabetes." (PMID 26473908, 2015). "In fact the results of our study would suggest that the application of exogenous polyamines has the potential to enhance the yield of in vitro generated insulin-producing β cells for the treatment of persons with diabetes, and is therefore an avenue of current investigation." (PMID 26299433, 2015). "Average diabetes duration varies across the groups with different treatment types from 5.6 years in the group without antidiabetic medication to 16.2 years in the group with insulin treatment." (PMID 25859544, 2015). "When enquired of whether diabetes result from high blood glucose, 28.8% (n=40) said yes, and another 20.1% (n=28) said it is because of failure of body to produce insulin." (PMID 26925888, 2015). "We therefore view that the H2S-mediated increase in glycolysis is an adaptive mechanism for survival of β cells to chronic ER stress, along with the improved ER function and insulin production and folding, both critical factors controlling hyperglycemia in diabetes." (PMID 26595448, 2015). "Currently, diabetes teams are hesitant to discuss DEB with their patients, because they are afraid they might bring the association between insulin and weight control to mind of the adolescent." (PMID 26173476, 2015). "Along with insulin, therapeutic replacement of amylin, as originally suggested, is nowadays recommended for a more tight control of glycemia in individuals with either type 1 or type 2 diabetes mellitus (T1DM or T2DM, respectively)." (PMID 26448437, 2015). "For all-cause mortality and all-noncancer mortality, which can mostly be ascribed to macrovascular and microvascular complications of diabetes, there was a significant association with insulin use, regardless of the duration of its use." (PMID 26171401, 2015). "Within the subgroup of women with type 1 diabetes, those who: are younger; have lower weight; have longer duration of diabetes; and only use insulin for treatment, are more likely to report preconception care practices such as focusing on glucose control or family planning counselling." (PMID 25783639, 2015). "First, the programme only targets diabetes patients with insulin therapy." (PMID 26171143, 2015). "The CARE-HF data are consistent with the association of insulin use or requirement and worse outcome rather than diabetes diagnosis." (PMID 25880202, 2015). "Betel nut extract and arecoline also have diabetogenic potential on adipocytes that may result in insulin resistance and diabetes at least in part via the obstruction of insulin signaling and the blockage of lipid storage." (PMID 25695047, 2015). "In the PIVUS cohort, we found an association of homocysteine with fasting insulin [β = 0.056 (95% CI 0.021, 0.090), P = 0.001], but not with incident diabetes." (PMID 26664883, 2015).
diabetes (continued). "The observation of glucose intolerance contrasted with an earlier suggestion put forth by Mirsky and Perisutti in 1955 that transient IDE inhibition, by increasing circulating insulin levels, may be suitable as a treatment of diabetes." (PMID 26394692, 2015). "The present study found that increased levels of insulin and insulin resistance (typical of subclinical diabetes) among those without diabetes were associated with lower risk of prostate cancer death." (PMID 26250516, 2015). "Since IDE- inhibitors are known to assist treatment of Diabetes mellitus by enhancing insulin signalling; our analysis suggest that LT10 peptide might exhibit this novel mode of anti-diabetic activity apart from its known anti-lethal activity." (PMID 25816209, 2015). "Impaired insulin signaling in the liver leads to the failure of insulin to suppress gluconeogenesis through the FoxO1 pathway, leading to hyperglycemia and ultimately diabetes (Haas and Biddinger, 2009; Leavens and& Birnbaum, 2011)." (PMID 26067236, 2015). "Two interviewees said that the fact that missing an insulin injection does not cause any symptoms affects diabetes management." (PMID 26005688, 2015). "Similarly, presence of depressive symptoms was significantly high among the people who were using insulin for the treatment of diabetes compared to the participants using only medications." (PMID 26236749, 2015). "Post-index diabetes-related treatment costs were higher for all groups, compared to pre-index treatment costs, in line with the expectations of a more intense treatment regime after insulin initiation." (PMID 28702235, 2015). "Our data also confirmed that there is no significant change in serum insulin, c-peptide and uric acid levels among control, diabetes and diabetes associated with hypertension." (PMID 25894234, 2015). "This could be of physiological importance since diabetes is a condition in which insulin signaling is impaired, and it is accompanied by epidermal thinning in experimental rat models in vivo." (PMID 25647160, 2015). "Cardiovascular risk factors used for the study included metabolic risk factors (waist circumference, TG, HDL-C, fasting blood glucose, systolic and diastolic blood pressures), diabetes-related factors (insulin, HbA1c, HOMA-IR), and heart disease-related factors (AI, hsCRP, homocysteine, ApoB)." (PMID 26497880, 2015). "Hyperglycemia, the hallmark of diabetes, results from an impaired glucose uptake due to a lack of insulin production by pancreatic beta cell (type 1) or lack of insulin action (type 2)." (PMID 26720696, 2015). "AMPK regulates insulin action and is a drug target for diabetes and metabolic syndrome." (PMID 25993470, 2015). "Currently insulin and many synthetic drugs are used in diabetes treatment." (PMID 26345313, 2015). "Ketoacidosis may also develop during follow-up because of inadequate compliance with insulin treatment or increased insulin requirement during illnesses." (PMID 25800476, 2015). "Impaired insulin secretion and insulin resistance are needed for the development of diabetes." (PMID 26561346, 2015). "However, it was estimated that of 13.2 million people with diabetes, only 162,000 were insulin pump users in 2002." (PMID 28702234, 2015). "Additionally, circadian disruption accelerated diabetes development in diabetes-prone rats due to apoptosis of insulin secreting β-cells." (PMID 25834642, 2015). "It is not likely that these three drugs have a path to clinical application for in vivo diabetes therapy, although the pathways they target might eventually be exploited in vitro to increase insulin yields for cell therapy applications." (PMID 27019722, 2015). "Diabetes mellitus is a chronic disease due to a failure in both producing and using insulin." (PMID 26033326, 2015).
diabetes (continued). "The prevalence of vitamin D deficiency in obese individuals is over 80 %, and the presence of vitamin D receptors and the responsiveness of insulin gene expression to vitamin D in human pancreatic β cells suggest a role of vitamin D in β cell function and diabetes." (PMID 26202330, 2015). "The increased magnesium content in UO could delay the onset of diabetes as reported in OLETF rats where an increased magnesium intake of 16 mg/day improved insulin sensitivity and glucose utilisation." (PMID 25648511, 2015). "Investigations on how insulin stimulates the sodium pump may help to understand the pathophysiology of diabetes and diabetes-induced hypertension." (PMID 25854427, 2015). "Mammalian target of rapamycin (mTOR) is activated by insulin and insulin-mediated breast cancer progression in patients with type 2 diabetes mellitus may be abrogated by inhibition of mTOR." (PMID 26537234, 2015). "However, consistent with our findings, numerous studies have shown that insulin requirements and plasma and capillary blood glucose levels can be reduced using a diabetes-specific EN formula as an adjuvant to insulin." (PMID 26549276, 2015). "“Avoiding” such as avoiding insulin injections or avoiding to talk about having diabetes." (PMID 25928592, 2015). "Recently, we analyzed 368 hospitalized patients at Hospital das Clínicas da Faculdade de Medicina da Universidade de São Paulo and 23 % of patients had previous diagnosis of diabetes mellitus, but only 1 % of them had received basal-bolus as insulin therapy regimen." (PMID 26697118, 2015). "Furthermore, since eHSP70 and iHSP70 are directly related to insulin sensitivity, R value application in diabetes appears to be straightforward." (PMID 25814786, 2015). "Our findings confirm a previous report of an association between copeptin and incident diabetes independent of fasting insulin and fasting blood glucose and extends this to older adults aged >60 years." (PMID 26158609, 2015). "We aimed to evaluate the efficacy and safety of the three dipeptidyl peptidase 4 (DPP-4) inhibitors (vildagliptin, sitagliptin, and linagliptin) as add-on therapy in Chinese patients with type 2 diabetes mellitus (T2DM)inadequately controlled on dual combination of insulin and metformin or acarbose." (PMID 26500706, 2015). "Our results also showed that insulin treatment could partially reverse the deleterious effects of diabetes on implantation rate." (PMID 26002932, 2015). "However, this review contained just one trial in young children aged 6–15 years with diabetes duration of 1–2 years, and most of the other included trials were conducted in the 1980s, when use of insulin pump therapy was less widespread." (PMID 26563100, 2015). "Given the large impact that individual behaviors have on diabetes control, such as diet, energy expenditure, blood glucose monitoring, medication adherence, and self-adjustment of insulin doses, the standard of diabetes care includes self-management education and support." (PMID 25830952, 2015). "Both of the pregnant women with type 2 diabetes mellitus required insulin treatment." (PMID 25789781, 2015). "Cdr1as may represent a useful tool in addressing the growing request of new therapeutic strategies based upon insulin secretion and β cells renewal in diabetes." (PMID 26211738, 2015). "This significantly decreased insulin activity in diabetes and treated obesity." (PMID 25756784, 2015). "While insulin is an effective treatment for hyperglycemia, it carries the potential for undesirable side effects such as hypoglycemia and weight gain, which in turn can lead to a worsening ability to manage diabetes." (PMID 26060825, 2015). "We found that two SNPs in human LEFTY1 were nominally associated with altered insulin release in a glucose tolerance test, but not with glycaemia or diabetes." (PMID 26348837, 2015).
diabetes (continued). "Interestingly, several micro-RNAs (miRNAs) have been found to be differentially expressed in tissues relevant for insulin signaling and resistance (liver, skeletal muscle, adipose tissue, and pancreatic beta cells) during obesity, hyperglycemia, and diabetes." (PMID 26470795, 2015). "Many patients with diabetes are adept at managing their home insulin regimen." (PMID 26429339, 2015). "Diabetes implication: Bupropion-zonisamide treatment has also been linked to decreased fasting insulin, but currently, there is not enough available research to confirm its cardiometabolic safety profile." (PMID 25894803, 2015). "Peroxisome proliferator-activated receptor gamma (Pparγ) participates in adipocyte differentiation, glucose and insulin homeostasis, and inflammation, and it was suggested that it plays an important role in several diseases, including obesity, diabetes, and atherosclerosis." (PMID 25802864, 2015). "Adherence to oral diabetes medications in T2D patients is 36 to 93% and to insulin is around 60%." (PMID 26053004, 2015). "Sixteen participants reported insulin use for control of their diabetes." (PMID 26554457, 2015). "In those with established diabetes, insulin omission, whether deliberate or unintentional, is the most common precipitating factor for DKA." (PMID 25889476, 2015). "The patients were being treated with insulin, and the duration of diabetes was at least 10 years." (PMID 25780477, 2015). "The possible increase of insulin in diabetic liver may be due to the presence of extra pancreatic insulin-producing cells in liver especially during diabetes and hyperglycemic states." (PMID 26110898, 2015). "This lowers the effect of therapeutic insulin, which is typical for diabetes mellitus type 2." (PMID 26524638, 2015). "In the Framingham data, the maximal negative correlation observed between Asn concentration and fasting insulin also extends to additional diabetes metrics such as body mass index (BMI), waist circumference (WC), homeostatic model assessment (HOMA), and triglyceride levels." (PMID 26178806, 2015). "However, as reported by our group and others, Japanese pre-diabetes and early-stage diabetes are both characterized by reduced insulin secretion along with lower insulin resistance when compared to Caucasians." (PMID 25944304, 2015). "Those with diabetes may change drug regimens regularly and may switch from oral medications to insulin as their disease progresses." (PMID 25785731, 2015). "For diabetes, oral hypoglycemic drugs and insulin were available in the health centers." (PMID 26711290, 2015). "Overall, this will decrease the amount of INSRB homodimers, and may have a significant impact on insulin-mediated metabolic signalling in obesity and diabetes." (PMID 25742416, 2015). "Indeed, in vitro transduction of B13 cells with Ad-PNM reprogrammed said cells into insulin-producing cells, which were able to relieve diabetes upon transplantation into NOD-SCID mice." (PMID 26690959, 2015). "Therefore, for the purpose of this review we are going to focus on the role of CHP in insulin physiology in relation to diabetes." (PMID 26703752, 2015). "Health care professionals are frequently challenged with the task of motivating patients to follow dietary and exercise guidelines and take insulin injections to improve their diabetes control and thereby slow or avoid the occurrence of diabetes-related acute and chronic complications." (PMID 24607084, 2014). "However, when insulin initiation is eventually needed it is often delayed in part because the majority of PwT2D are referred to specialist physicians and diabetes nurse educators (DNEs)." (PMID 25361788, 2014). "Although a range of other interactive simulation programs of glucose-insulin interaction in diabetes have been described in the literature, to date, most of these do not seem to have been distributed so widely via the internet or been made particularly widely available." (PMID 24511312, 2014).
diabetes (continued). "Diabetes mellitus (DM) is a multifactorial metabolic disorder characterized by chronic hyperglycemia with disturbances of carbohydrate, fat, and protein metabolism resulting from defects in insulin secretion and/or insulin action." (PMID 25089145, 2014). "Recent advances enable the induction of stem cells, such as ES and iPS cells, to differentiate into insulin-producing cells, which may serve as an alternative cell source for cell transplantation therapy in diabetes." (PMID 24743240, 2014). "At baseline, participants in the delayed intervention arm reported that they were taking either insulin (15.6%) or other medications (76.0%) for the treatment of diabetes; in the immediate intervention arm, 20.9% were taking insulin and 27.8% were taking other medications." (PMID 24576395, 2014). "This will go a long way to improving their attitude towards insulin therapy and diabetes in general, coping strategies and invariably quality of life, and in the long run change their practices to embrace healthier lifestyles along with adhere to insulin therapy." (PMID 24397956, 2014). "β cells are the most numerous islet cell types and their identity as source of insulin was established in 1938 when the β cells of dogs with diabetes (induced by anterior pituitary extract rich in growth hormone) were found to be extensively deregulated or destroyed." (PMID 25945127, 2014). "Diabetes mellitus is characterized by hyperglycemia that involves abnormalities in either insulin secretion or action at peripheral tissues, resulting in reducing insulin sensitivity at skeletal muscle and adipose and liver tissues, which represents insulin resistance." (PMID 24550994, 2014). "Independently of diabetes, glypican 4, clusterin, chemerin and progranulin are related with parameters of insulin sensitivity, suggesting that these adipokines may play a role in the development of insulin resistance." (PMID 24968098, 2014). "The present study strengthened the link between diabetes and lung cancer; and supported a lack of association with insulin use." (PMID 24991802, 2014). "Diabetes mellitus (DM) is an endocrine and metabolic disorder characterized by dyslipidemia, hyperglycemia and protein metabolism that result from malfunction in regulating either insulin secretion or insulin action." (PMID 25072202, 2014). "Considering the risk involved in inappropriate insulin use, attention to evaluating knowledge of insulin use is important because nowadays insulin requiring diabetes patients are encouraged to own insulin delivery kits so as to ensure timely administration of basal insulin." (PMID 24397956, 2014). "However, in model containing sex, age, and 2-hour insulin, PPARG allele T was significantly associated with a lower prevalent diabetes risk with an odds ratio of 0.56 (95% CI: 0.31–0.95)." (PMID 25197274, 2014). "Conventional treatment with insulin was able to correct the weight gain and metabolic changes in diabetic animals, without, however, correcting and / or preventing damage to the thin fibers caused by STZ-induced diabetes." (PMID 24387617, 2014). "Moreover, certain diabetes drugs that boost insulin sensitivity only work if adiponectin is present in the body." (PMID 25339419, 2014). "RYGB surgery improved liver insulin sensitivity –as measured by HOMA-IR– regardless of diabetes status, while remission of T2DM was associated with normalisation of fasting plasma insulin concentrations and HOMA-IR values." (PMID 25539584, 2014). "In addition, six (11.5%) patients developed pneumothorax prior to death and 26 (53.1%) developed diabetes that required insulin treatment after the administration of high-dose corticosteroid therapy." (PMID 25176016, 2014). "Excess body weight in women with PCOS may accelerate progression toward diabetes by exacerbating both insulin resistance and inappropriate insulin-response." (PMID 24705280, 2014). "They concluded that orally administered insulin prevents diabetes in transgenic mouse." (PMID 26556194, 2014).